CRP (C-reactive protein)
Diseases named in the same sentence as CRP in open-access papers (continued):
Sharing a sentence is not in itself a finding about the gene and the disease.
diabetes (continued). "However, recent studies have demonstrated through biological and proinflammatory analyses of TNF-α, IL-6, CRP and MMP that this cytokine storm condition directly influences systemic conditions or diseases, such as diabetes and CVD." (PMID 36984510, 2023). "Small but statistically significant differences in sex, BMI, smoking status, education level, diabetes, cam morphology, dysplasia, and CRP were deemed not clinically relevant." (PMID 37937087, 2023). "Both diabetes and HIV drive elevated levels of C-reactive protein as seen from our results, however, IL-6 could be better marker than CRP for the inflammation seen with diabetes and even in HIV co-morbidity." (PMID 37545969, 2023). "Regarding medical variables, the low phosphorus group had a higher percentage of diabetes, lower diastolic pressure, lower concentrations of urea, creatinine, albumin, cCa, PTH, and CRP, and higher levels of glucose, triglycerides, and residual renal function (RRF)." (PMID 37497059, 2023). "Moreover, we find CRP, GGT1, GPT, and GDF15 to be highly enriched for multiple disease terms related to cardiovascular diseases and diabetes in the GLAD4U disease database." (PMID 37590326, 2023). "After further adjusting for diabetes, hypertension, familial CVDs, smoking and drinking history, TC, LDL-C, HCY, Hs-CRP, number of coronary lesions and stent implantation in model 3, the TyG index still remained independently associated with one-year endpoints (P < 0.001)." (PMID 38017540, 2023). "In Model 2, after further controlling for education years, hypertension, diabetes, stroke subtypes, baseline NIHSS score, and Hs-CRP levels, an increased SII index also significantly correlated with 3-month PSCI (per 1-SD increase, OR, 2.341; 95% CI, 1.439–3.809; p = 0.001)." (PMID 36979274, 2023). "Further, C1M correlated to female sex, age, BMI, triglycerides, non-HDL cholesterol, CRP, diabetes and IL-6." (PMID 37714678, 2023). "Serum PAB, hs‐CRP concentration, and lipid profile were significantly different between postmenopausal women with and without diabetes mellitus." (PMID 36577716, 2023). "Previously, our team reported that within the CRP range of <10 mg/L, elevated CRP is significantly associated with PAD and renal microvascular dysfunction in West Africans without diabetes." (PMID 37664733, 2023). "Population-based studies assessing CRP as a marker for future diabetes incidences have not been reported for the Scandinavian countries." (PMID 37775289, 2023). "Lactic dehydrogenase levels were elevated in the diabetes group, 312 mg/dL, versus 223 mg/dL (p = 0.00029), which suggests an increased inflammation in diabetes patients, confirmed by CRP values (64.9 mg/dL vs. 31.4 mg/dL in non-diabetes group, p = 0.0022)." (PMID 37627906, 2023). "Populations with ideal overall CVH tended to be younger, female, with better socioeconomic status, of white ethnicity, higher education level, no history of drinking alcohol, lower CRP, and no history of diabetes or CVD (P < 0.05)." (PMID 36930331, 2023). "In the sensitivity analyses, the results did not significantly change when further adjusted for lipid-lowering drugs, CRP levels, and sleep pattern score or after excluding incident CHD events within 2 years among individuals with diabetes and individuals with prediabetes." (PMID 37513593, 2023). "Increased CRP levels are a sensitive serological test for the diagnosis of DCM because they represent cardiac injury to some extent and indicate the likelihood of co-infection in patients with DCM compared to those with diabetes alone." (PMID 36871006, 2023). "The participants with diabetes had significantly higher inflammation as assessed by CRP concentrations relative to participants without diabetes (3.2 [1.6, 7.1] mg/L vs. 1.8 [0.9, 4.3] mg/L, p < 0.0001)." (PMID 37891943, 2023).
diabetes (continued). "P-NfL levels in the highest quartile were found to be a significant predictor of incident CKD after adjustment for age, sex, education, hypertension, diabetes (model II) and additional adjustments for smoking, BMI, fasting plasma glucose, LDL cholesterol, CRP, and homocysteine (model III)." (PMID 37225431, 2023). "The groups were also similar for preoperative infection indicators (WBC, CRP and PCT), mean age at diagnosis, body mass index, sex ratio, history of hypertension and diabetes, stone essence, degree of hydronephrosis, urine culture, and history of preoperative ESWL (all P > 0.05)." (PMID 37483661, 2023). "In contrast to ENPP7, we find that CRP, FAS, and GDF15 are the most studied targets for diabetes." (PMID 37590326, 2023). "The two groups displayed significant differences in clinical data such as age, sex, educational level, hypertension, current drinker, SBP, DBP, height, BMI, WC, duration of diabetes, FPG, HbA1c, hemoglobin, leukocytes, gamma-glutamyl transferase, ALB, TG, TC, hs-CRP, ACR, and eGFR." (PMID 37645414, 2023). "Patients with HF, CAD, low LVEF, low triglycerides, high CRP, and high eGFR were associated with lower SFRP5 levels independent of age, BMI, or diabetes after multivariate analysis (overall model r = 0.729, SE = 0.638)." (PMID 37504530, 2023). "Compared with the patients without NAFLD, the former group exhibited a higher proportion of males and higher smoking rates, a greater prevalence of family history of CVD, diabetes and hypertension, elevated BMI, uric acid, ALT, AST, TG, hs-CRP, and APRI levels, as well as a lower HDL-C level." (PMID 37952443, 2023). "The slope for the relationship between BMI and ln hs-CRP was stronger in people without diabetes was greater than that in people with diabetes (β = 0.099 and β = 0.055, respectively), but both slopes were significantly different than zero (p < 0.001)." (PMID 37215204, 2023). "Furthermore, COPD group and normal group had significant differences in these variables: race, education levels, PIR, smoking status, history of diabetes, hypertension and CVD, WBC counts, CRP, and SII index(P < 0.01)." (PMID 37563621, 2023). "Age, gender, BMI, smoking, duration of diabetes, hypertension, low-density lipoprotein cholesterol (LDL-C), hypersensitive C-reactive protein (hs-CRP), anemia, diabetic neuropathy, DN, ASCVD, low education, OAD, insulin, and ACEI/ARB were included as covariates in the multivariable analysis." (PMID 38020197, 2023). "There was also a greater proportion of people with high blood pressure, high cholesterol, diabetes, and CRP in the CVD group compared to the non-CVD group." (PMID 37630735, 2023). "Inflammatory markers were higher in diabetes patients (CRP average value 63.3 mg/dL vs. 38.7 mg/dL in the non-diabetes group)." (PMID 37627906, 2023). "The results of our study showed that the risk of major amputation in patients with diabetes after ACT with no-option CLTI is increased by inherited thrombophilia—MTHFR A1298C gene mutations, smoking, and higher CRP levels before ACT treatment." (PMID 35450383, 2022). "For the outcome Mortality, those are f6M= [C.H.D., Age, Urea, hsTnI, CRP, Creatinine], f10M=f6M∪ [LDH, Neutrophil, WBC, Hb]; for the outcome Severity, we have instead f6S= [Hypertension, Diabetes Mellitus, Age, CRP, LDH, hsTnI] and f10S=f6S∪ [Lymphocyte, Creatinine, Urea, Neutrophil]." (PMID 36359571, 2022). "This study showed that there is an inverse correlation between the PhA and CAC score in patients on PD, even after adjusting for several variables such as age, sex, diabetes, glomerular filtration rate, BMI, hemoglobin, physical activity, calcium x phosphorus, PTH, and ultrasensitive CRP." (PMID 35990362, 2022). "In addition, macroalbuminuria was associated with disability in ADL (OR = 1.94, 95%CI: 1.24–3.03) and there was an interaction effect between elevated CRP and albuminuria on ADL disability among older adults with diabetes." (PMID 36003971, 2022).
diabetes (continued). "The current study also reveals that serum levels of inflammatory markers CRP were tremendously increased in the patients with diabetes (35.308 ± 1.32) mg/dl than in non-diabetic patients (18.6365 ± 0.64) mg/dl." (PMID 36268329, 2022). "The study model was adjusted for age, sex, baseline eGFR, urine albumin to creatinine ratio, diabetes mellitus, prevalent cardiovascular disease, LDL-cholesterol, HDL-cholesterol, smoking, body mass index, systolic and diastolic blood pressure, C-reactive protein and serum albumin." (PMID 36291168, 2022). "Compared with participants in the lower METS-IR group, those with higher METS-IR showed higher SBP, DBP, BMI, TG, LDL-C, Hs-CRP, creatinine, fasting glucose, HbA1c, TG/HDL-C and TyG index, lower HDL‐C, and a higher percentage of male, smoking, diabetes, hypertension and CAC." (PMID 36357872, 2022). "They had neither fasting hyperglycemia nor diabetes nor elevated hs-CRP (high-sensitivity C-Reactive Protein) nor hypertension." (PMID 35311446, 2022). "Patients with GO had a higher BMI, levels of fasting plasma glucose, HOMA-IR, and hs-CRP, and they were more likely to have diabetes or pre-diabetes and hyperlipidemia compared to those without GO." (PMID 36556950, 2022). "We found that age, LDH, CRP, WBC count, lymphocyte count, oxygen saturation, the history of malignancy, COPD, diabetes, chronic cardiac disease, chronic kidney disease, cerebrovascular disease, and non-vaccination were all independent predictors for critical illness." (PMID 36601398, 2022). "Therefore, screening of neutrophil counts, CRP, ALP, serum lactate and albumin levels is advised in diabetic cancer patients infected with SARS-CoV-2." (PMID 36059615, 2022). "We identified eight known targets of hospital management to be significantly associated with hospitalisation independently from age and gender: diabetes, dyspnea, procalcitonin≥0.2 ng/mL, MDW ≥ 22, saturation < 96%, D-dimer≥0.72 mg/L, prothrombin time < 95% and CRP ≥ 21 mg/L." (PMID 35986291, 2022). "There were significant differences in BMI, WBC, TC, TG, HDL-C, LDL-C, and CRP among participants with or without diabetes diagnosed by 2020 guidelines (P > 0.05)." (PMID 36163072, 2022). "Dengue-infected individuals with diabetes showed greater CRP, Endocan levels, IL-8 and Perfusion Index than those without diabetes (CRP; 35.308 ± 1.32 vs. 18.6365 ± 0.64) mg/dl (p≤ 0.001) (Endocan 42.316 ± 1.46vs." (PMID 36268329, 2022). "But quite a few indicators, such as albumin, PAB and CRP were not statistically different, suggesting that good glycemic control can reduce the adverse effects of diabetes to some extent." (PMID 35308284, 2022). "Consistent with previous studies, serum albumin and pre-albumin are lower in sarcopenia than in the non-sarcopenia group, but not sex, BMI, dialysis duration, diabetes, and Hs-CRP." (PMID 36458164, 2022). "Variables, including sputum purulence, increased sputum volume, diabetes mellitus, FEV1, % predicted, PCT ≥ 0.07 ng/mL, Neu ≥ 6.41 × 10^9/L, CRP ≥ 15.8 mg/dL, OPN ≥ 13.26 ng/mL, and SCS treatment, were retained as covariates in the forward stepwise selection procedure of multivariate analysis." (PMID 35400078, 2022). "We included all the variables with a p-value less than 0.05 into the multivariate logistic regression model (including monthly frequency of HD, sex, diabetes, BUN, Scr, TG, LDL-c, HDL-c, phosphorous, iron, PTH, vitamin D, NT-proBNP, hemoglobin, CRP, Kt/V urea, and ferritin)." (PMID 36562038, 2022). "In this study, we disentangled GxE interaction from RxE interaction using a large sample size for diabetes-related metabolic traits such as glucose, HbA1c and CRP that were not studied before." (PMID 35356427, 2022). "Patients with abnormally high QRS-T angles were older and had higher prevalence of diabetes as well as myocardial infarction, higher left ventricular mass index (LVMI) and C-reactive protein, worse oxidant/antioxidant status, and lower ejection fraction and HSP27." (PMID 35633658, 2022).
diabetes (continued). "Patients with higher serum OPG levels presented with higher mortality rates compared to patients with lower levels, and in multivariate analysis, OPG was a marker of general and cardiovascular mortality independent of sex, age, CVD, diabetes, and CRP levels." (PMID 35814784, 2022). "For those aged 75+, we observe an English disadvantage for depression, ADLs, pain, and poor SRH not observed among those under 75, while for those under 75 we observe a U.S. disadvantage in clinical diabetes and CRP not observed among those aged 75+." (PMID 35217868, 2022). "HR(95%CIs) for all-cause and cause-specific mortality according to serum 25(OH)D,Cadmium and CRP among participants without diabetes." (PMID 35571939, 2022). "The patients with type 2 diabetes mellitus showed increased suPAR values in all the time periods (suPAR-1, suPAR-3 and suPAR-7) and in CRP-3 and CRP-7 values in comparison with the patients without diabetes." (PMID 35330458, 2022). "In individuals without diabetes, inflammation reflected by increased CRP levels and insulin levels precedes glucose intolerance." (PMID 35757631, 2022). "The participants with the highest tertile of Gensini score had higher levels of BMI, WBCs, neutrophils, CRP, HbA1c, Cr, NHR, and higher prevalence of diabetes, but lower levels of HDL-C and less alcohol drinkers, compared to those with the lowest tertile of Gensini score (all P for trend < 0.05)." (PMID 36505389, 2022). "Decedents also tended to be older, with lower levels of BMI, with higher prevalence of previous diabetes, myocardial infarction, CKD, and chronic heart failure, and with higher levels of heart rate, FPG, HbA1c, hs-CRP, the peak value of cTnI, and peak value of NT-proBNP." (PMID 35911514, 2022). "CRP has been well established to serve as a sensitive marker of acute inflammation, and recent studies have also demonstrated its significance in chronic inflammatory diseases like CVD and diabetes mellitus." (PMID 36140236, 2022). "In that study, CRP enabled differential diagnosis of HNF1A-MODY, with a receiver operating characteristic curve-derived C-statistic for discrimination between HNF1A-MODY and other diabetes types of 0.86 (95% confidence interval: 0.83, 0.88)." (PMID 36104811, 2022). "Previous studies have reported that increased secretion of tumor necrosis factor α (TNFα), interleukin (IL)-6, C-reactive protein (CRP), and other substances at low concentrations lead to chronic low-grade inflammatory responses accompanied by the development and progression of diabetes mellitus." (PMID 35062863, 2022). "A total of 5020 adults above 20 years of age without diabetes who had completed at least one day 24-h dietary recall interview, body adiposity measurement, HbA1c level, and CRP examination were selected for final analysis." (PMID 36613000, 2022). "As an indicator of chronic inflammation, Hs-CRP is not alone and is accompanied by diabetes and age." (PMID 36005411, 2022). "Patients with HRPR are more likely to have a medical history of hypertension (p = 0.053) and diabetes and have lower levels of WBC, Hb, and eGFR as well as higher levels of PLT, LDL-C, HDL-C, hs-CRP, and C1q (178.49 ± 31.11 mg/L vs. 168.56 ± 31.57 mg/L, p < 0.001) at baseline laboratory data." (PMID 36248871, 2022). "The inflammatory variables (C-reactive protein, Endocan, Interleukin-8 and Perfusion Index) were also checked in both the groups i.e., dengue with diabetes and dengue without diabetes." (PMID 36268329, 2022). "However, the associations of venular tortuosity with HbA1c, WCC, granulocyte count, CRP and TFMI in the present study were modified by diabetes status, meaning that the slopes were different for those with and without diabetes." (PMID 35852586, 2022). "The results showed that the GMP intervention group could further reduce the inflammatory reaction induced by diabetes by reducing the levels of IL-6, TNF-α, and CRP and increasing IL-10." (PMID 35399678, 2022).
diabetes (continued). "CRP has been well established to serve as a sensitive marker of acute inflammation, and recent studies have demonstrated its significance in chronic inflammatory diseases including CVD and diabetes mellitus." (PMID 36140236, 2022). "Moreover, elevated levels of C-reactive protein (CRP), tumor necrosis factor-α (TNF-α), IL-6, IL-18, and IL-1β were reported among patients with type 2 diabetes mellitus displaying features of the insulin resistance syndrome." (PMID 34917685, 2021). "This study showed that the CRP, IL-6, TNF-α levels in saliva were higher in diabetics than healthy controls, supporting the hypothesis that the pathogenesis of type 2 diabetes mellitus involves subclinical chronic inflammation." (PMID 33676486, 2021). "The change in venular calibre correlated with initial white cell and neutrophil counts (p both < 0.01), but not with initial CRP, serum albumin, gender, hypertension, diabetes, smoking history dyslipidaemia, haemoglobin level or renal function (p all NS)." (PMID 34446820, 2021). "The objective of the present study was to examine the independent association between fasting insulin and the inflammatory marker CRP in individuals without diabetes." (PMID 33691751, 2021). "One clinical trial indicated that eight weeks of probiotic yogurt treatment significantly reduced the TNFα level, but while levels of IL-6 and CRP were also decreased, these findings were not statistically significant among those with diabetes." (PMID 33557067, 2021). "Neither demographic characteristics, including age, gender, hypertension, diabetes, smoking, and BMI, nor clinical examinations, including creatinine, hs-CRP, lipoprotein (a), ejection fraction (EF), and left ventricular diameter, were significantly different." (PMID 34354549, 2021). "Comparison was performed among the three groups: sex, age, MA(ADP), leukocyte count, hs-CRP, smoking history, ACS, hypertension, diabetes mellitus, prior myocardial infarction, prior PCI, hemoglobin, platelet count, LDL-C, TC, glucose and eGFR were significantly different (P all <0.05)." (PMID 34671655, 2021). "Our collected data indicated that, compared to the non-diabetic group, patients with diabetes had higher NLR as well as higher levels of CRP, ESR, LDH, and blood glucose." (PMID 33746672, 2021). "Other parameters like diabetes, hypertension, duration of HD, body mass index, hemoglobin, eGFR, ejection fraction, high sensitivity CRP and albumin did not significantly affect SPAP, which were determinants for PH." (PMID 33816034, 2021). "The differences in age, sex, diabetes, smoking, drinking, BMI, WBC, TC, and LDL-C in the CHD group were not statistically significant (P > 0.05), but the differences in hypertension, TG, HDL-C, ApoA1, and CRP levels were statistically significant (P < 0.001)." (PMID 34235188, 2021). "Despite being a well-recognized inflammatory biomarker, in our study, CRP was not affected by menopause nor diabetes." (PMID 34568498, 2021). "Regardless of diabetes mellitus, the independent risk factors for death included dyspnea, neutrophil, PLT count, and CRP." (PMID 34164413, 2021). "Adiposity indices, smoking and C reactive protein only partially explained the differences in diabetes prevalence between studies in women and did not explain differences between diabetes prevalence in men." (PMID 33664061, 2021). "While the associations with diabetes and aspirin are consistent with the lower level of CRP found in APOE-ε4 carriers, their effects are unexpected in that diabetes and high levels of CRP have been reported as associated with an elevated risk of neurodegenerative diseases." (PMID 34301914, 2021). "The negative impact of CRP on survival is not limited to cancer but is observed in cardiovascular disease, diabetes mellitus, chronic obstructive pulmonary disease, etc.." (PMID 34350956, 2021).